CACYBP (calcyclin binding protein)
Diseases named in the same sentence as CACYBP in open-access papers (continued):
Sharing a sentence is not in itself a finding about the gene and the disease.
CACYBP also shares sentences with these, for which no sentence is quoted: osteogenic sarcoma (4 papers); cholangiocarcinoma (2); hypertension (2); lung adenocarcinoma (2); lung carcinoma (2); neurodegenerative disease (2); prostate carcinoma (2); acute lymphocytic leukemia (1); Angelman syndrome (1); bladder tumor (1); Clear Cell Renal Cell Carcinoma (1); frontotemporal dementia (1); Intellectual disability (1); nasopharyngeal carcinoma (1); promyelocytic leukemia (1); pulmonary arterial hypertension (1); Turner syndrome (1); urothelial carcinoma (1).